UGT1A1 (UDP glucuronosyltransferase family 1 member A1)
Diseases named in the same sentence as UGT1A1 in open-access papers (continued):
Sharing a sentence is not in itself a finding about the gene and the disease.
Gilbert syndrome (continued). "Gilbert’s syndrome is a mild, usually asymptomatic, and relatively frequent (5% of the population) benign liver disease characterized by a partial deficit, between 20 and 70%, of the activity of the UGT1A1 isoform that causes an increase in bilirubin levels." (PMID 36422890, 2022). "Several polymorphisms in the promoter and coding region of the UGT1A1 gene complex has been described, which was associated with reduction in UGT1A1 enzyme activity and Gilbert syndrome phenotype-an autosomal recessive unconjugated hyperbilirubinemia (UCH) disorder." (PMID 36520959, 2022). "Gilbert’s syndrome is an inherited disease caused by decreased activity of UGT1A1." (PMID 35883814, 2022). "In addition, the authors performed a Mendelian randomization analysis of the main UGT1A1 single-nucleotide polymorphism (SNP) associated with Gilbert’s Syndrome." (PMID 34771701, 2021). "On further follow-up, there was mild, intermittent jaundice due to genetically proven Gilbert syndrome (homozygosity for seven TA repeats in the TATA box of the promoter of the UGT1A1 gene, as is typically associated with Gilbert syndrome: A(TA)7TAA/A(TA)7TAA)." (PMID 33684277, 2021). "To investigate the considerable increase in bilirubin in the proband (tot 5.3, ind 4.9), which was modest in the mother (tot 1.7, ind not available) and brother (tot 1.1, ind 0.9), we carried out the analysis of the UGT1A1 gene, to evaluate the presence of mutations causing Gilbert’s Syndrome." (PMID 32751969, 2020). "The patient also had UGT1A1 deficiency and hence Gilbert’s syndrome." (PMID 30898145, 2019). "For patients with Gilbert syndrome, 85% (47/55) harbored pathogenic variants of UGT1A1⁎60." (PMID 31467903, 2019). "UGT1A1 deficiency is associated with Gilbert’s syndrome and increases the toxicity of irinotecan." (PMID 30898145, 2019). "The UGT1A1*28/*28 is the most common genotype associated with Gilbert’s syndrome within Caucasian and African populations whereas the UGT1A1*6/*6 (rs4148323, 211 G > A) genotype, is almost exclusively encountered in the Asian populations with a MAF for the UGT1A1*6 allele around 13–16%14." (PMID 29743555, 2018). "In addition, the patient displayed a mutation in UGT1A1 indicating Gilbert syndrome and total and indirect bilirubin was elevated." (PMID 29761093, 2018). "Given the absence of any significant organ toxicity of STA-12-8666 at the doses used in rodents, pancreatic and other cancers arising in the carriers of Gilbert syndrome allele of UGT1A1 could be highly sensitive to STA-12-8666." (PMID 27779106, 2017). "While increased UCB levels are so far the only identified outcome in Gilbert’s Syndrome, we cannot exclude that UGT1A1 mutations might exhibit other effects on human health." (PMID 26926838, 2016). "The high incidence of the UGT1A1*28 allele might lead to high risk of developing jaundice in the setting of Gilbert syndrome when exposed to specific PIs." (PMID 22506127, 2012). "Thus, we suggest that this UGT1A4 intronic SNP can be used as a genotyping marker for the Gilbert Syndrome allele of UGT1A1*27." (PMID 22514612, 2012). "Gilbert syndrome is caused by defects in bilirubin UDP-glucuronosyltransferase (UGT1A1)." (PMID 20529348, 2010). "Although UGT1A1*28 association with decreased gene expression and Gilbert syndrome is well documented, and could be observed in the current study, the inter-genotype differences were not significant, possibly due to a relatively small number of samples and considerable interindividual variability." (PMID 34741761, 2022). "Additionally, 83% (20/24) of patients with Gilbert syndrome heterozygous for UGT1A1⁎60 had an association with heterozygous variation of UGT1A1⁎28 or UGT1A1⁎81, while 91% (21/23) of Gilbert syndrome patients homozygous for UGT1A1⁎60 had biallelic variations of UGT1A1⁎28 and UGT1A1⁎81." (PMID 31467903, 2019).
Gilbert syndrome (continued). "Gilbert’s syndrome is characterized by mutations to the UGT1A1 gene located on the long arm (q) of chromosome 2 (2q37) which encodes the enzyme uridine disphosphate-glucuronosyltransferase-1A1 (UGT1A1) which is required for the conjugation and subsequent excretion of bilirubin." (PMID 30717703, 2019). "One of the most common genotypes causing Gilbert's syndrome in Caucasian populations is the inheritance of a promoter region containing an extra TA dinucleotide [A(TA)7TAA], which results in a 70% reduction in transcriptional activity compared with wild-type UGT1A1 [A(TA)6TAA]." (PMID 15280927, 2004). "For Gilbert syndrome, the mean Vmax of UGT1A1 was set to 4.60 μmol/L/min, which is 0.75% of the value in the healthy‐state reference model." (PMID 41543361, 2026). "In Gilbert syndrome and Crigler‐Najjar syndrome, UGT1A1 activity is decreased, whereas MRP2 activity is reduced in Dubin‐Johnson syndrome." (PMID 41543361, 2026). "A major difference to the previous work is that in our model UGT1A1 activity in Gilbert syndrome only represents 0.75% of the healthy reference." (PMID 41543361, 2026). "Subsequently, genetic testing confirmed two UGT1A1 variants, the c.-3279T>G hotspot (G/G) and A(TA)7TAA variant in the TATA box, consistent with a diagnosis of Gilbert syndrome." (PMID 39996891, 2025). "Gilbert syndrome is characterized by reduced activity of the UGT1A1 enzyme, which impairs bilirubin conjugation and leads to its accumulation." (PMID 41356983, 2025). "It is puzzling that despite the initial exclusion of patients with Gilbert disease, a high incidence of alterations in the UGT1A1 enzyme was found in the final study sample." (PMID 39518062, 2024). "Subsequent genetic analysis for Gilbert’s syndrome revealed that he was homozygous for seven thymine-adenine (7TA) repeats in the promoter region of the UGT1A1 gene, consistent with a diagnosis of Gilbert’s syndrome." (PMID 39502751, 2024). "Individuals with Gilbert’s Syndrome (GS), characterized by mild bilirubin elevation due to UGT1A1 gene abnormalities, exhibit lower body weight and reduced rates of diabetes and cardiovascular diseases." (PMID 39020370, 2024). "Patients with a diagnosis of Gilbert’s disease were excluded, but the incidence of the different UGT1A1 haplotypes in the entire sample was subsequently investigated." (PMID 39518062, 2024). "In this report, we document a unique liver injury characterized by an elevated bilirubin with normal alanine transaminase and aspartate transaminase levels in a patient who is homozygous for the UGT1A1 consistent with Gilbert syndrome." (PMID 37151737, 2023). "The key bilirubin metabolism gene, namely, the hepatic bilirubin conjugating isoenzyme UDP glucuronosyltransferase family 1 member A1 (UGT1A1) was classically described for Crigler-Najjar type I and II syndrome as well as Gilbert syndrome." (PMID 34074250, 2021). "Bilirubin is an endogenous substrate for UGT1A1 and Gilbert syndrome is characterized by abnormally high levels of circulating unconjugated bilirubin due to reduced UGT1A1 activity in carriers of the UGT1A1*28 allele." (PMID 28098838, 2017). "The presence of 7-TA nucleotide repeats in the (TA)nTAA promoter region of UGT1A1 (UGT1A1*28) leads to decreased expression of this gene, resulting in high plasma bilirubin levels that form the basis for Gilbert’s syndrome." (PMID 24650752, 2014). "Finally, the UGT1A1*27, also associated with the Gilbert Syndrome, has a complete linkage with the 1A4 intronic SNP c.867+101G>T (1A4*1d) (D’ = 1, R2 = 1), suggesting that, in addition to 1A1*27, the 1A4*1d can be used as a genotyping marker for the Gilbert Syndrome." (PMID 22514612, 2012). "The highest prevalence of these complications occurs in patients with Gilbert's syndrome because of the combined effect of increased bilirubin production and reduced bilirubin-diphosphate-glucuronosyltransferase (UGT1-A1) enzyme activity." (PMID 20942922, 2010).
Gilbert syndrome (continued). "The upstream region of UGT1A1 was analyzed in patients with Gilbert syndrome and in normal Japanese and Caucasian subjects." (PMID 20529348, 2010). "UGT1A1 activity in patients with Gilbert syndrome was about 30% of normal, based on studies involving human liver samples." (PMID 20529348, 2010). "Literature estimates UGT1A1 activity in Gilbert syndrome as 30%–50% of normal." (PMID 41543361, 2026). "However, patients with Gilbert’s disease (UGT1A1) were excluded, limiting the evidence on this aspect, as were patients with central nervous system metastases." (PMID 39518062, 2024). "Therefore, it appears that Gilbert’s disease is only one manifestation of a more generalized alteration in UGT1A1 enzyme function in these patients." (PMID 39518062, 2024). "Individuals with genetic polymorphisms in UGT1A1 exhibit bilirubin levels that belie their risk of liver disease (Gilbert's syndrome) but it is not known if this phenomenon extends to other common liver blood tests (LBTs)." (PMID 39425533, 2024). "Contrasting with Gilbert syndrome are Crigler–Najjar syndromes, which are rare conditions characterized by the disrupted or absent function of the UGT1A1 enzyme due to assorted genetic mutations." (PMID 38474028, 2024). "It turns out that both Crigler-Najjar and Gilbert syndromes are caused by a lack of glucuronosyltransferase (UGT1A1), which is responsible for the conversion of bilirubin to bilirubin diglycosidic acid, making bilirubin less soluble in water." (PMID 38651155, 2024). "Defects in UGT1A1 may impair the glucuronidation of bilirubin and may be responsible for Gilbert’s syndrome (GS; On-line Mendelian Inheritance in Man database [OMIM] No. 143500)." (PMID 36274106, 2023). "In addition, 20 patients were diagnosed with a genetic hyperbilirubinemia syndrome: Dubin-Johnson syndrome (ABCC2, n = 17), Rotor syndrome (SLCO1B1/B3, n = 1), Crigler-Najjar syndrome (UGT1A1, n = 1) and Gilbert syndrome (UGTA1, n = 1)." (PMID 35626323, 2022). "However, it is possible that an impairment of UGT1A1, responsible for Gilbert’s syndrome, is masked by the combined activity of the other isoforms since in vitro studies showed that EtG formation is catalyzed by a variety of UGTs." (PMID 36422890, 2022). "Individuals with Gilbert’s syndrome are estimated to have only 25–30% of normal UGT1A1 activity." (PMID 33805415, 2021). "The most common genotype in the general population is 6/6 UGT1A1*1, characterized by six homozygous repeat dinucleotides; the presence of 7/7 UGT1A1*28, typical of patients with Gilbert's syndrome, is instead characterized by a glucuronation efficiency as low as 30-50% than the normal." (PMID 29861877, 2018). "As expected, significantly lower serum bilirubin concentrations between FD patients and control subjects were observed within all UGT1A1 genotypes, with the lowest values in UGT1A1 [TA]6/6 wild types and the highest in UGT1A1 [TA]7/7 Gilbert's syndrome genotypes." (PMID 28951772, 2017). "One disease that is characterized by reduced UGT1A1 activity is Gilbert’s syndrome." (PMID 23388413, 2013). "A mild increase of serum bilirubin levels is also observed in the Gilbert syndrome, a benign condition caused by a TA-insertion in the TATA box of UGT1A1 promoter [A (TA)7TAA] (termed UGT1A1*28; instead of the normal TA6), leading to 50%–70% reduction in UGT1A1 gene expression." (PMID 38826804, 2024). "Similarly, no such association was found in the pediatric study from Taiwan (where, however, the UGT1A1*28 gene variant is not the major mutation responsible for Gilbert syndrome manifestation)." (PMID 34943103, 2021). "Accordingly, the effect of the UGT1A1 and OATP1B1 inhibitor atazanavir on bilirubin levels was evaluated using models for healthy individuals and patients with Gilbert syndrome." (PMID 41543361, 2026).
Gilbert syndrome (continued). "Patient 2 [F508del/R553X, UGT1A1*28 7/7] had a direct relative with Gilbert’s syndrome and was therefore screened prior to starting ETI therapy; genetic testing showed that they were positive for UGT1A1." (PMID 38956524, 2024). "However, defects of hepatic uptake transporters might contribute to pathogenesis, as pointed out in a study on subjects displaying the Gilbert's syndrome but no UGT1A1 mutations." (PMID 29259555, 2017). "Homozygosity at the polymorphic promoter repeat locus UGT1A1*28 leads to decreased ability of the UGT1A enzyme to metabolize bilirubin and subsequent mild hyperbilirubinuria (also known as Gilbert's syndrome)." (PMID 22416852, 2012). "Furthermore, we also investigated the effect of the UGT1A1 and OATP1B1 inhibitor atazanavir in healthy individuals and patients with Gilbert syndrome." (PMID 41543361, 2026). "This variant is in the promoter of the UGT1A1 gene, 310 bp upstream of the (TA)n repeat UGT1A1*28 (rs3064744) at the TATA box, which is known to reduce the expression of UGT1A1 enzyme on Gilbert-Meulengracht ́s Syndrome, drifting into reduced bilirubin glucuronidation." (PMID 38826804, 2024). "Dual-hereditary jaundice (Dubin–Johnson syndrome (DJS) and Gilbert’s syndrome (GS)) is a rare clinical entity resulting from defects of the ATP binding cassette subfamily C member 2 (ABCC2) and UDP glucuronosyltransferase family 1 member A1 (UGT1A1) genes with autosomal recessive inheritance." (PMID 36274106, 2023). "Unlike patients with Crigler–Najjar syndrome, in which UGT1A1 activity is barely detected, mildly elevated unconjugated bilirubin levels are observed in patients with Gilbert’s syndrome, who are usually asymptomatic." (PMID 35883814, 2022). "The [TA]6/7 genotype appears to contribute as a blocker of diet-induced gene transcription but does not correlate to Gilbert's syndrome, whereas the [TA]7/7 genotype does not appear to play a role in diet-induced antioxidative UGT1A1 transcription but in the prevalence for Gilbert’s syndrome." (PMID 25606436, 2014).
neutropenia (136 papers, 2008 to 2026). A decrease in the number of neutrophils found in the blood. "UGT1A1 poor metabolizers are at increased risk of severe toxicity, particularly neutropenia and diarrhea, when treated with a standard dose of irinotecan." (PMID 40936312, 2026). "Treatment with SG in UGT1A1*28 homozygous subjects increased the risk of any‐grade neutropenia, diarrhea, and anemia." (PMID 40936312, 2026). "In contrast, UGT1A1*6 remained significantly associated with an increased risk of all-grade neutropenia in the first cycle and severe neutropenia in both cycles (p < 0.002)." (PMID 41385496, 2025). "Our study found that the incidence of all-grade neutropenia during the first cycle was higher in patients with the TA7 allele (UGT1A1*28) compared to those with the TA6 allele (p = 0.008)." (PMID 41385496, 2025). "Patients homozygous for the UGT1A1*6 allele (UGT1A1*6/*6 genotype) are at a high risk for grade 4 (G4) neutropenia." (PMID 40430836, 2025). "The UGT1A1 phenotype, including intermediate and poor metabolizers, was linked to a higher incidence of all-grade neutropenia during the first cycle (p < 0.001) and severe neutropenia during the second cycle (p < 0.001)." (PMID 41385496, 2025). "Applying the stringent Bonferroni correction (p value < 0.002), our findings demonstrated a significant association between irinotecan-induced neutropenia and the UGT1A1*6 and UGT1A1 phenotypes, as well as the ABCC2 c.-24C > T variant, in relation to toxicity." (PMID 41385496, 2025). "As certain toxicities, particularly neutropenia and diarrhoea, have been associated with the reduced metabolism of SN-38 in patients carrying specific UGT1A1 polymorphisms, we considered the potential influence of this pharmacogenetic factor in our cohort." (PMID 41007623, 2025). "The findings suggested that haplotypes associated with decreased area under the curve (AUC) ratios and an increased risk of neutropenia included UGT1A1-6 or UGT1A1-28." (PMID 40432911, 2025). "Patients who are homozygous for the UGT1A1-28 allele are 3.5 times more likely to experience severe neutropenia compared to those with the standard genotype." (PMID 40432911, 2025). "The UGT1A1*6 was significantly associated with both all-grade and severe neutropenia in the first cycle (p < 0.001) and severe neutropenia in the second cycle (p < 0.002)." (PMID 41385496, 2025). "In terms of toxicity, UGT1A1*6 was significantly associated with both all-grade and severe neutropenia in the first cycle (p < 0.001) and severe neutropenia in the second cycle (p < 0.002)." (PMID 41385496, 2025). "Certain UGT1A1 polymorphisms (UGT1A1*28 and UGT1A1*93) have been shown to be associated with reduced enzyme activity and an increased risk to develop neutropenia." (PMID 40597074, 2025). "Several clinically relevant variants were identified: DPYD rs2297595 occurred more frequently than in European cohorts, and UGT1A1 rs8175347 was observed at a higher prevalence, underscoring the potential risk of irinotecan-related neutropenia and diarrhea." (PMID 41300713, 2025). "Both UGT1A1-6 and UGT1A1-28 variants were closely connected to Irinotecan-induced severe neutropenia." (PMID 40432911, 2025). "Our study demonstrated that intermediate and poor metabolizers of UGT1A1 were significantly associated with both all-grade and severe neutropenia in the first and second cycles." (PMID 41385496, 2025). "Conversely, the SLCO1B1*5 variant (rs4149056) is associated with decreased transporter activity, resulting in higher SN-38 plasma concentrations and an elevated risk of neutropenia, particularly in combination with UGT1A1*28 variant alleles." (PMID 41385496, 2025). "The U.S. Food and Drug Administration (FDA) label for irinotecan includes a warning for patients carrying the UGT1A1 *28/*28 genotype due to their increased risk of severe neutropenia." (PMID 41385496, 2025).